TEAD1 (TEA domain transcription factor 1)
Diseases named in the same sentence as TEAD1 in open-access papers (continued):
Sharing a sentence is not in itself a finding about the gene and the disease.
multiple myeloma (1 paper, 2020). "A possible example is the TEAD1 gene, which is known to be over-expressed in aggressive and treatment-refractory cases of multiple myeloma and which showed de novo ASM in its upstream enhancer region in a multiple myeloma case in our series, via gain of a new TF binding motif on the mutated allele." (PMID 32594908, 2020).
Myocardial fibrosis (1 paper, 2025). "In addition, transcription factors such as Tead1 and Hdac2 can be verified by further experiments in the future to find their potential association with adverse outcomes such as myocardial fibrosis." (PMID 40595870, 2025). "Tead1 and Hdac2 may be potential targets for inhibiting myocardial fibrosis and preventing adverse outcomes of MI after further experimental verification." (PMID 40595870, 2025).
myopia (1 paper, 2023). "Tead1 is a transcription factor associated with multiple myopia-related bioactivities and pathways, such as glycolysis, Wnt signaling and cellular growth." (PMID 36975502, 2023). "Combined with myopia-related TFs, Tead1 was the only TF intersected by the three groups." (PMID 36975502, 2023). "Although most of these functions were validated in non-ocular tissues, the mutation of Tead1 was responsible for pathologic syndromes, with myopia as a manifestation, which indicates that Tead1 might play a role in the local regulatory networks." (PMID 36975502, 2023). "Taken together, Tead1 might be the upstream regulator of miR-671-5p and several target genes in myopia development." (PMID 36975502, 2023). "In addition to the downstream mechanisms of miR-671-5p, we identified Tead1 as an upstream regulator of miR-671-5p in terms of myopia modulation by in silico prediction." (PMID 36975502, 2023). "In addition to the downstream mechanisms, Tead1 was identified as a possible upstream regulator of miR-671-5p in myopia development." (PMID 36975502, 2023). "Finally, Tead1 was identified as a possible upstream regulator of miR-671-5p in myopia development." (PMID 36975502, 2023).
Myotonia (1 paper, 2025). An involuntary and painless delay in the relaxation of skeletal muscle following contraction or electrical stimulation. "Notably, exon skipping events in Yap1 and Tead1 were detected exclusively in mice without myotonia, absent in those with myotonia." (PMID 41000779, 2025). "In Mbnl1−/− mice without myotonia, uniquely mis-spliced genes are predominantly associated with cytoskeleton organization and the Yap-Tead complex, comprising the transcription factor YAP1 and its coactivator TEAD1, both of which respond to mechanical stimuli (right dot plot)." (PMID 41000779, 2025).
Nephropathy (1 paper, 2024). A nonspecific term referring to disease or damage of the kidneys. "Moreover, we have shown that knockout of Taz or Tead1 in macrophages reduces the severity of IRI nephropathy in mice." (PMID 39108258, 2024). "Thus, we assumed that knockout of Tead1 in macrophages attenuates IRI nephropathy." (PMID 39108258, 2024).
neuroblastoma (1 paper, 2020). Neuroblastoma (NB) is the most common solid, extracranial childhood tumor. "We expressed Tead1-flag or Tead2-flag with either HA-tagged Yap1 or HA-tagged Taz in neuroblastoma cells (N2A) and performed co-immunoprecipitation experiments." (PMID 32170161, 2020).
neuropathy (1 paper, 2024). A disorder affecting the nervous system that manifests with pain, tingling, numbness, and/or muscle weakness. "Because of the neuropathy, Tead1 cKO mice were humanely euthanized before P60." (PMID 38456457, 2024).
osteoarthritis (1 paper, 2021). A noninflammatory degenerative joint disease occurring chiefly in older persons, characterized by degeneration of the articular cartilage, hypertrophy of bone at the margins and changes in the synovial membrane. "Several of these SNVs, rs3771501 (TGFA), rs3993110 (TEAD1/DKK3), rs72979233 (CHRDL2), and rs7967762 (PFKM/WNT10B), are associated with multiple osteoarthritis joint sites." (PMID 34450027, 2021).
ovarian serous cystadenocarcinoma (1 paper, 2025). A malignant serous cystic epithelial neoplasm arising from the ovary. "Further localization analysis also showed that TEAD1 was significantly highly expressed in tumor cells in BRCA, KIRC, and ovarian serous cystadenocarcinoma (OV)." (PMID 40539054, 2025).
pancreatic disorders (1 paper, 2019). "Previous studies indicate that effectors of the Hippo signaling system including TEAD1 and its transcriptional activator YAP are integral components of the embryonic development of human pancreas and its expression is recapitulated during progression of pancreatic disorders." (PMID 31849712, 2019).
pancreatitis (1 paper, 2022). Inflammation of the pancreas. "We next focused on examining the expressional patterns of PAF1, YAP1, and TEAD1 in cerulein-induced wild-type (WT) and KrasG12D, Pdx-1 Cre (KC) pancreatitis mouse models." (PMID 36180487, 2022).
pulmonary fibrosis (1 paper, 2024). Chronic progressive interstitial lung disorder characterized by the replacement of the lung tissue by connective tissue, leading to progressive dyspnea, respiratory failure, or right heart failure. "Overall, our study revealed that the YAP1/TEAD1-Prdx3 axis inhibits lung senescence, promotes cell survival and lung repair, and alleviates pulmonary fibrosis." (PMID 38945958, 2024). "Hence, we elucidated that targeting the YAP1/TEAD1-Prdx3 axis may be an effective therapeutic strategy for pulmonary fibrosis." (PMID 38945958, 2024). "Silencing of Prdx3 abolished the beneficial effects of YAP1, indicating the vital role of the YAP1/TEAD1-Prdx3 axis in inhibiting cellular senescence and maintaining cell survival, whereas overexpression of Prdx3 in AT2 cells alleviated pulmonary fibrosis." (PMID 38945958, 2024). "Overall, we propose the role of the YAP1/TEAD1-Prdx3 axis in regulating AT2 cell senescence and pulmonary fibrosis, revealing a novel strategy for the treatment of pulmonary fibrosis." (PMID 38945958, 2024). "In this study, we first revealed that increased expression of YAP1 in AT2 cells mitigated BLM-induced pulmonary fibrosis and revealed the regulatory relationship between YAP1/TEAD1 and Prdx3." (PMID 38945958, 2024).
retinal dystrophies (1 paper, 2025). "The case highlights the importance of clinical-genetic correlation in the interpretation of rare variants and expands the phenotypic and geographic spectrum of TEAD1-associated retinal dystrophies." (PMID 40984966, 2025).
tumor (66 papers, 2008 to 2026). "Subsequent investigations should concentrate on the molecular mechanisms underlying TEAD1`s function, its potential in the tumor immune microenvironment, and its potential as a therapeutic target." (PMID 40539054, 2025). "Third, although we observed associations between TEAD1 and the tumor immune microenvironment, the specific immunomodulatory mechanisms merit further investigation." (PMID 40539054, 2025). "High levels of Taz and Tead1 were also co-expressed in gastric epithelial and tumor cells and in cancer-associated fibroblasts." (PMID 37957015, 2024). "For example, we found that certain genes, such as HMGA1 or TEAD1, are recurrently associated with GPCRs' expression across multiple tumor subtypes." (PMID 38723607, 2024). "In addition, TEAD1 was associated with the infiltration level of specific subsets of immune cell, thereby influencing the composition of the tumor microenvironment." (PMID 40539054, 2025). "Although we found that decreased expression of ITGA1, ITGA2, or TEAD1 correlated with PCa severity, it remains unclear whether loss of these three genes have synergistic effects on tumor severity compared with loss of either individual gene." (PMID 38169150, 2024). "In addition to histological studies, our current study included analyses of TEAD1 mRNA levels and genomic deletion or loss of TEAD1 with all the data supporting a tumor suppressive function for TEAD1 in PCa." (PMID 38169150, 2024). "Therefore, our work has deciphered a novel mechanism by which TEAD1 regulates α1‐ and α2‐integrin expression and thereby exerts tumor suppressive functions while loss of TEAD1 and/or ITGA1/ITGA2 in PCa genomes were found to correlate with disease progression and aggressiveness." (PMID 38169150, 2024). "NSUN2 modifies the 3’-UTR of TEA domain transcription factor 1 (TEAD1) mRNA through m5C, promoting TEAD1 expression and thereby enhancing tumor cell proliferation and invasion." (PMID 40370440, 2025). "We elucidated the transcription factor–target gene regulatory network involving NKX2-1 and TEAD1 in malignant tumor cells derived from AT2 cells." (PMID 41415280, 2025). "FOXM1, a transcription factor involved in cell proliferation, interacts with YAP through TEAD1 to regulate genes essential for tumor growth." (PMID 41256331, 2025). "TEAD1 coordinates and integrates multiple signaling pathways, and its downregulation affects the expression of various oncogenes involved in tumor cell progression, metastasis, and resistance to chemotherapy." (PMID 40370440, 2025). "Highly consistent with the localization results, the expression level of TEAD1 was significantly positively correlated with the content of tumor cells in the spot." (PMID 40539054, 2025). "We observed that TEAD1 expression in tumor cells was dominant in multiple cancer types, including BRCA, CRC, and LIHC." (PMID 40539054, 2025). "The first was a congenital SSRMS tumor in the forearm of a 2-week-old girl with a TEAD1::NCOA2 gene fusion (case 7), and the second was an intraosseous SSRMS in the base of the skull of a 12-year-old boy with a FUS::TFCP2 gene fusion (case 8)." (PMID 40923514, 2025). "The study also demonstrated that inhibiting p300 activity via a small molecule inhibitor led to reduction in TEAD1::NCOA2 colony formation along with suppressing tumor growth in the allograft model." (PMID 40599857, 2025). "Some TFs were specific for individual cell lines, others were shared between two cell lines, and a total of eight TFs were shared amongst all three tumor types, including TEAD1, TEAD2, TEAD3, TEAD4, GRHL2, RUNX2, AP1, and GATA6." (PMID 38912065, 2024). "Our findings indicated that elevated levels of MKLN1-AS in PDAC act as a competitive endogenous RNA (ceRNA) by interacting with miR-185-5p, resulting in enhanced cell proliferation, migration, and tumor development through the modulation of TEAD1 expression." (PMID 38740637, 2024).
tumor (continued). "An integral component of the Hippo signaling pathway, TEAD1 is known for its involvement in processes such as tumor cell proliferation, migration, epithelial-mesenchymal transition, and drug resistance." (PMID 38740637, 2024). "Among the neoantigens are well-known genes associated with tumor progression and metastases, such as HAUS3, NSDHL, MAGEA10, FNDC3B, TEAD1, DHX33, PGM5, and MLL2." (PMID 36607962, 2023). "TEAD1, the most studied member of TEADs, is known to promote cell proliferation and migration in tumor progression." (PMID 35739490, 2022). "It is well established that non-phosphorylated YAP can be transported into the nucleus and interact with TEAD1–4 to activate multiple downstream target genes, which is very important to enhance tumor proliferation and apoptosis inhibition." (PMID 36131287, 2022). "NSUN2 modified 3'UTR of TEA domain transcription factor 1 (TEAD1) mRNA with m5C which promotes the expression of TEAD1, thereby enhancing the proliferation and invasion of tumor cells." (PMID 35562754, 2022). "We also examined the effects of HNK on YAP1 and TEAD1 expression in the tumor tissues from the AOM/DSS treated mice." (PMID 34206989, 2021). "BT-474.r2T cells were xenografted in a heterotopic mouse model to further examine the role of YAP1 and TEAD1-2 in tumor growth to evaluate in vivo the potential antitumor activity of verteporfin alone or in combination with trastuzumab." (PMID 32365528, 2020). "To gain mechanistic insight into how TEAD1 regulates tumor migration, we overexpressed AQP4 and CDH11 in sham and TEAD1KO spheroids and studied their migratory behavior." (PMID 30275445, 2018). "TEAD2 and 4 were significantly upregulated in HNSCC samples as compared to their non-tumor counterparts, while TEAD1 and TEAD3 were markedly downregulated in cancerous samples relative to non-tumor samples." (PMID 30459528, 2018). "Four TFs with enriched tumor-specific motifs showed high gene expression (top 25th percentile) of which only TEAD1 was differentially overexpressed in E+GSCs." (PMID 30275445, 2018). "We uncover two distinct regulatory GSC signatures, a developmentally shared/proliferative and a tumor-specific/migratory one in which TEAD1/4 motifs are uniquely overrepresented." (PMID 30275445, 2018). "Histological analysis at 3.5 months after transplantation, a relatively early time point in PDX formation, confirmed tumor engraftment in both sham and TEAD1KO cells as well as the stable loss of TEAD1 protein in TEAD1KO cells." (PMID 30275445, 2018). "YAP1 is an activator of TEAD1–4 transcription factors and it has been found that TEAD1–4 family members play important role in tumor progression via activating progression-inducing genes (CTGF, Cyr61, and Myc)." (PMID 29850494, 2018). "miR-124 affects the ability of tumor cells to survive under O2 and/or nutrient deprivation in part by directly regulating TEAD1, which is among factors involved in cell proliferation and survival under stress." (PMID 26041995, 2015). "Strikingly, with the exception of Tead1, bothalleles of all of these genes were targeted by inserts in primary tumours inthis screen, indicative of key tumour promoting events." (PMID 24252690, 2013). "c-Cbl was expressed in the cytoplasm of epithelial tumour cells, whereas TEAD1 was confined to the nuclei." (PMID 19002168, 2008). "In addition, at the protein level, we also observed significantly high expression of TEAD1 in LIHC tumor samples." (PMID 40539054, 2025). "Upstream tumor suppressors, including MST1, LATS1/2, and FAT1/2/3/4, frequently undergo deletions or mutations, whereas downstream oncogenes such as YAP1, WWTR1, and TEAD1/2/3/4 are upregulated." (PMID 41256331, 2025). "The relationship between TEAD1 expression and tumor metastasis was further verified." (PMID 40539054, 2025). "In addition, we analyzed the anti-cancer immune status of the TEAD1 high and low expression groups at seven different stages of the tumor immune cycle." (PMID 40539054, 2025).
tumor (continued). "We observed that the high TEAD1 expression group exhibited active downregulation at multiple stages of the tumor immune cycle, which may lead to reduce the infiltration levels of effector immune cells." (PMID 40539054, 2025). "Next, we investigated the role of TEAD1 in the impacts of MKLN1-AS on tumor cell aggressiveness." (PMID 38740637, 2024). "Interestingly, TEAD1 emerged as the top candidate gene that was co‐expressed with ITGA1/ITGA2 in the TCGA cohort consisting of 498 localized PCa tumor samples." (PMID 38169150, 2024). "Moreover, we also observed that decreased TEAD1 expression levels were significantly correlated with PCa severity, including advanced tumor stage, higher Gleason score, lymph node metastasis and PSA levels." (PMID 38169150, 2024). "AP000695.2 promotes the glycolysis of LUAD by regulating the miR-335-3p/TEAD1 axis, and it may serve as a potential target of anti-tumor energy metabolism therapy." (PMID 37723874, 2023). "Furthermore, TEAD1 was found to be the upstream regulator of several signaling pathways, including tumor angiogenesis, the cell transformation signature, and VEGFA-EGFR2 signaling, indicating its possible role in driving the pro-angiogenic phenotype." (PMID 34824203, 2021). "The Wnt‐induced transcriptional gradient of YAP mRNA expression is sufficient to explain the resulting gradient of YAP protein along the crypt‐villus axis, as well as the elevation of YAP protein observed in Apc mutant tumours, while the Wnt‐induced TEAD1/2/4 mRNA expression is even more potent." (PMID 33950519, 2021). "Subsequently, we verified that TEAD1, a transcriptional coactivator of Yes-associated protein 1 (YAP1), directly bound to the HIF1A promoter region and the YAP1 and TEAD1 proteins co-regulated the expression of HIF1A, thus promoting tumour glycolysis." (PMID 33218358, 2020). "According to previous investigations and bioinformatics predictions, HIF1A could promote tumour glycolysis, and its promoter region might have a DNA binding motif for TEAD1, a transcription coactivator of YAP1." (PMID 33218358, 2020). "In the tumor cells at metastatic locations, we detected meta-program IV (MAP2, GRIK2), a hallmark of neuron development, and meta-program I, the mesenchymal-neuroblast-like (MES-Nbt) state, which was enriched for genes related to the EMT such as ZEB1, ZEB2, and TEAD1." (PMID 41279557, 2025). "Moreover, we found that in response to intracellular accumulation of lactate, AARS1 translocated into the nucleus, where it directly catalyzed lactylation of YAP at K90 and TEAD1 at K108, thereby activating downstream target gene expression to promote tumor cell proliferation." (PMID 38512451, 2024). "We are currently verifying whether expression of putative target human genes, located in the vicinity or at the site of integration, is modified in tumour cells, notably TEAD1 which was reported to be used by another Polyomavirus, SV40, as a transcriptional enhancer factor." (PMID 20865165, 2010). "Here, our findings identified the ANLN/RhoA/YAP1/TEAD1 positive feedback axis in ICC, which was essential for cytokinesis and tumor growth." (PMID 41513610, 2026). "In a follow-up study characterizing spindle-cell infantile/pediatric RMS tumor specimens, additional fusions were identified including VGLL2::NCOA2, VGLL2::CITED2, TEAD1::NCOA2, and SRF::NCOA2." (PMID 40599857, 2025). "We found that the expression of TEAD1 in LIHC was significantly negatively correlated with the immune score, suggesting its critical role in suppressing tumor immune responses." (PMID 40539054, 2025).